TNF (tumor necrosis factor)
Diseases named in the same sentence as TNF in open-access papers (continued):
Sharing a sentence is not in itself a finding about the gene and the disease.
tumor (continued). "Additionally, the sialoglycan on the surface of tumor cells impedes the secretion of TNF-α by Siglec-9 positive macrophages while promoting the secretion of IL-10." (PMID 37645415, 2023). "M1‐type macrophages could secrete pro‐inflammatory cytokines and chemokines (e.g., IL‐6, IL‐12, and TNF‐α) for antigen presentation and tumor cell clearance." (PMID 36999977, 2023). "Inflammatory conditions, tumor necrosis factor, tumor environment, etc., activate TFs." (PMID 37280670, 2023). "Helper T lymphocytes (Th) 17 are capable of promoting tumour angiogenesis through the production of pro-inflammatory and pro-angiogenic mediators, such as IL17, IL-8 and TNF-a, while the tumour microenvironment also mediates Th17 cell chemotaxis and accumulation at the tumour site." (PMID 36968098, 2023). "Furthermore, NK cells can produce cytokines, such as IFN-γ and TNF-α, which can enter tumour cells and thus kill them." (PMID 38130720, 2023). "For example, activation of the PI3K-Akt signaling pathway inhibits proliferation, migration, and infiltration of tumor cells and promotes apoptosis, while the TNF signaling pathway inhibits proliferation, migration, and infiltration of tumor cells and promotes apoptosis." (PMID 38102307, 2023). "Additionally, C60(OH)x-treated macrophages generated more tumor necrosis factor alpha in vitro, implying that C60(OH)x can boost innate immunity in tumor-bearing mice, thereby limiting the development of tumors." (PMID 37047572, 2023). "Researchers indicated that removing soluble TNF-alpha receptors local enhancement of endogenous TNF-alpha activity may provide for enhanced tumor cell death." (PMID 37259026, 2023). "However, when patients with HCC were classified according to tumor stage (based on Okuda’s classification), circulating TNF-α was higher in more advanced stages of the disease." (PMID 37958479, 2023). "Indeed, antibiotic treatment impaired the production of TNFα and other cytokines by immune cells including monocytes, macrophages, and dendritic cells, and reduced tumor regression." (PMID 38046824, 2023). "A caveat is that once bone marrow-derived macrophages enter the tumor, the expression of chemokine receptors may be downregulated, as has been shown in ovarian cancer, where CCR2 expression is regulated by tumor-derived TNF." (PMID 37822933, 2023). "Patients consuming the KD with chemotherapy were found to have reduced tumor sizes by an additional 21mm, lower cancer staging, increased anti-tumorigenic factors of IL-10, reduced factors that promote angiogenesis such as TNF-alpha, insulin, and IGF-1, and a higher survival rate." (PMID 37937022, 2023). "Some proinflammatory cytokines, such as IL-6, IL-1β, and TNF-α, are secreted by macrophages, which may contribute to tumor-promoting inflammation." (PMID 37211559, 2023). "For example, Astragaloside IV, as an active extract of Astragali Radix, could inhibit the growth and proliferation of tumor cells and induce apoptosis of tumor cells, and promote immunity by regulating levels of IL-1β, IL-6, and TNF-α cytokines." (PMID 37907925, 2023). "Some studies pointed out the direct relation between TNF-α and tumor growth." (PMID 36903346, 2023). "Given that TNFα is present in the tumour microenvironment, the administration of ML-60218 systemically could have an effect locally in the tumours, thus having a lower impact on other tissues." (PMID 36900285, 2023). "Further transcriptomic analysis revealed that the anti-tumor effects of PKU12-based siRNA delivery may be associated with modulating of HIF-1 signaling, TNF signaling, NF-kappa B signaling, ferroptosis, IL-17 signaling pathways." (PMID 37350944, 2023). "TNF‐α is involved in many physiological and pathological processes, such as cellular proliferation or differentiation, regulation of immunologic, vascular invasion and destruction of tumour vasculature." (PMID 37431884, 2023).
tumor (continued). "In addition, VEGF and TNF production from N2 TANs promote tumor vascularization and Matrix Metalloproteinases (MMP)-9 secretion, which participates in the tumor extracellular matrix reconstruction and contributes to subsequent tumor metastasis." (PMID 37063873, 2023). "EMT can be induced by different factors (TGFβ1, TNFα, etc.)secreted by different cells in a tumor." (PMID 37108080, 2023). "Intratumoral administration of TNF resulted in a significant reduction in tumor cells in mice." (PMID 37046608, 2023). "After intertumoral injection of cGAMP, a macrophage phenotype-like cell subset that produced TNF-α, displayed phagocytic activity and expressed high levels of T-cell recruiting chemokines, were transiently accumulated in the tumor microenvironment of CRC mice model." (PMID 37781354, 2023). "Previous studies have shown that TAMs in HCC tumor stroma produce various proinflammatory cytokines, including TNF-α, IL-β, IL-6 and IL-23, which induce the expansion of CD4+ Th17 cells, according to the overexpression of PD-L1, CTLA4 to inhibit antitumor immunity." (PMID 37745297, 2023). "In addition to active cell migration to form stable conjugations with target cells, CAR-T cells can produce various cytokines, such as TNFα and IFNγ, in the tumor microenvironment." (PMID 37388744, 2023). "The combinations of receptor-ligand pairs among different TNF/TNFR family members may have diverse effects on the tumor microenvironment, and these interactions may play a critical role in mediating immune evasion, immune activation, and immune surveillance." (PMID 38149239, 2023). "TNF- α can also promote tumor lymphangiogenesis and lymphatic metastasis." (PMID 37006260, 2023). "Moreover, IL-17 and TNF signaling pathways are primarily involved in inflammation, tumor cell proliferation, and immune regulation." (PMID 37950195, 2023). "However, in recent years, small doses of TNFα, such as those produced by the tumor, have been considered a possible tumor-promoting agent." (PMID 36996146, 2023). "First, splenic HSPCs accompanying tumor presence express a gene profile characterized by TNFα." (PMID 37134077, 2023). "Moreover, NK cells differentiate tumors through the production of IFN-γ and TNF-α leading to decreased expansion and progression of cancer, in addition to the conditioning of T cells to target tumor cells." (PMID 37197660, 2023). "In addition, autocrine TNF-α upregulates PD-L1 expression in tumor cells, further inhibiting the activation of antitumor lymphocytes." (PMID 37291128, 2023). "Finally, a cleavage fragment of COL6A3 known as endotrophin recruits macrophages through induction of monocyte chemoattractant protein-1 (MCP1) and increases IL-6 and TNFα in the tumor microenvironment." (PMID 36901727, 2023). "Although named for its antitumor properties, TNFα also has tumour-promoting properties." (PMID 36900285, 2023). "As a result, they may secrete a series of immunosuppressive factors, including indoleamine 2,3-dioxygenase, TGF-β, TNFα, IFNγ, prostaglandin E2, which can help tumor cells escape from immune surveillance." (PMID 36835844, 2023). "B94, a direct target of TNF-α, is aberrantly expressed in human cancers and could promote cell proliferation, angiogenesis, and metastasis in tumor cells." (PMID 36820951, 2023). "The high (60%) incidence of complete clinical tumor response in patients with TNFα induction can be explained by the possible switching on of signal transduction involving the interaction of TNFα with its cell receptors leading to the activation of the apoptotic pathway." (PMID 37979032, 2023). "Additionally, the activated T cells secrete cytokines like TNF‐α, which reduces the expression of heat‐shock proteins in tumor cells and thus enhances the sensitivity of tumor cells to heat stress." (PMID 38018578, 2023).
tumor (continued). "TNF-α is predominantly produced by activated antigen-presenting cells and is a powerful tumoricidal cytokine, as its name describes, which induces the apoptotic cell death, stimulates the inflammatory response at the tumor sites and inhibits the tumorigenesis." (PMID 38259474, 2023). "These cytokines, including TNFα and IL‐10, may shift the threshold of immune subsets activation within the tumor micro‐environment, thereby resulting in augmented adaptive immune responses." (PMID 37737046, 2023). "PD-L1 staining may be observed on both infiltrating immune cells and tumor cells, and an abundance of type-I and type-II interferons, IL-12, IL-23, IL-1β, TNFα, IL-2, granzymes, CXCL9, CXCL10, and other pro-inflammatory/effector cytokines may also be observed." (PMID 37345086, 2023). "Tumor-associated macrophages may express pro-malignant mediators such as tumor necrosis factor-alpha, which may enhance the production of tumor-supporting molecules by tumor cells, such as matrix metalloproteinases." (PMID 36873124, 2023). "PD-L1 can alter TNFα-mediated tumor cell apoptosis into pyroptosis, leading to tumor necrosis." (PMID 37071001, 2023). "Moreover, interleukin-1β (IL-1β) and tumor necrosis factor-α (TNF-α) released by NB cell-repolarized M1-Mφs can also drive tumor cell proliferation through regulating arginine metabolism." (PMID 37040518, 2023). "Few studies have reported that TNF-α can stimulate MSCs to promote tumor development." (PMID 36814921, 2023). "Tumor-associated monocyte-derived DCs (MoDCs) possess a suppressive TIP-DC phenotype, preventing T cells from being potently activated by high expression levels of inducible nitric oxide synthase (iNOS) and TNF-α." (PMID 37631284, 2023). "In addition, a cytokine array of tumor lysates (n = 4 for each genotype) revealed a marked reduction in VEGF, indicating a reduction in tumor angiogenesis, and an increase in TNFα, indicating a more inflammatory tumor microenvironment." (PMID 37270599, 2023). "Importantly, the combined therapy enhanced the population of CD3 + T cells, CD8 + T cells, IFN-γ + CD8 + T cells, and TNF-α + CD8 + T cells markedly in the tumor region." (PMID 36539510, 2023). "Despite a sustained inflammatory response possibly being detrimental to suppressing precancerous lesions, increased TNF-α in a tumor microenvironment could effectively activate TNFR1 to trigger cancer cell suppression." (PMID 36674931, 2023). "Moreover, TNF-α levels are elevated in the AT of tumor-bearing rats, which contributes to muscle wasting and reduced AT mass." (PMID 37217930, 2023). "Moreover, vaccinated tumor-bearing mice exhibited increased TNFα levels and reduced levels of immunosuppressive chemokines/cytokines." (PMID 37645899, 2023). "Similarly, the protein level of TNF-α and NFκB in the tumor homogenates was significantly reduced by α-hederin or cisplatin compared to the EST control group." (PMID 36986504, 2023). "However, the accumulation of a high level of TNF-α in the tumor tissues exhibits potent anti-neoplastic actions which were in concordance with this study." (PMID 37338718, 2023).
tumor (continued). "Autophagy in the microenvironment is induced by Drosophila tumor necrosis factor and IL-6-like signaling from metabolically stressed tumor cells, and tumor growth is dependent on the active transport of amino acids produced by autophagy in microenvironmental cells." (PMID 38039297, 2023). "Moreover, TNF-α can produce ROS to induce DNA damage and contribute to tumor progression through angiogenesis." (PMID 38248096, 2023). "Cytotoxic CD8+ cells and NK cells secrete IFN-γ and TNF-α that induce tumor cell growth arrest." (PMID 36831498, 2023). "TNFα is a cytokine that is secreted by leukocytes, stromal, and cancer cells into the tumor microenvironment and may be induced by both immune and radiation therapies." (PMID 36831373, 2023). "This suggests that proinflammatory cytokines, such as TNF-α, produced in response to tumor growth and circulating through the bloodstream may enforce endothelial Notch1 signaling at distant sites." (PMID 37749321, 2023). "Thus, TNF-α signaling can suppress tumorigenesis as well as promote angiogenesis, migration, and invasion of tumor cells." (PMID 37233761, 2023). "Furthermore, this research also indicated that vitamin D inhibits tumour cell-induced release of tumour necrosis factor-alpha (TNF-α) and reduces intracellular transforming growth factor beta (TGF-β) levels." (PMID 38085380, 2023). "It has also been reported that TAMs affect the glycolysis of tumor cells by secreting TNF-α." (PMID 38022518, 2023). "However, there is also supporting evidence that there is immune enhancement in HPV-positive HNSCC, such as a high level of tumor immune cell infiltration and increased production of pro-inflammatory cytokines TNF-α and interferon-γ." (PMID 37504269, 2023). "On the other hand, it is also proposed that higher GM-CSF in the serum is related to the BC metastasis and increased production of GM-CSF in cancer patients (probably due to inflammatory milieu, i.e., in response to TNF-α and LPS), supports angiogenesis, and promotes tumor growth and progression." (PMID 37835465, 2023). "NF-κB activation is an essential mechanism of tumor cell resistance to antitumor drugs such as TNF." (PMID 37917013, 2023). "In addition, SFI reduced the levels of proinflammatory cytokines IL-2, IFN-γ, and TNF-α in spleen, However, the mRNA levels of IL-2, IFN-γ and TNF-α in tumor tissues were significantly increased, while IL-6 mRNA levels were significantly decreased." (PMID 37355637, 2023). "The activated p38 MAPK, in turn, promotes the production of cytokines (TGFβ and TNFα) and interleukins (IL-6, IL-8, and IL-1β) within the tumor microenvironment, all of which are known to play a role in promoting tumor growth, angiogenesis, invasion, and metastasis." (PMID 36993955, 2023). "Tumor-derived EVs carrying cell death receptors and their ligands can induce apoptosis on T cells by activating caspases 3 and 7; additionally, tumor-derived EVs can decrease the synthesis of TNF-α and Interferon gamma (IFN-γ) via Tc cells in a dose-dependent manner." (PMID 37175226, 2023). "Indeed, TNFα is a key mediator of cancer-related inflammation and is involved in tumor progression in the TME." (PMID 36996146, 2023). "On the other hand, MGL-mediated engagement of DCs with GalNAc-containing ligands can enhance DC cell activation and survival by activation of MAPK/ERK and NF-kappaB signalling, resulting in an increase of CD8+ T cell mediating anti-tumour response and secretion of IL-10 and TNF-α by DCs." (PMID 37612278, 2023). "TNF-a inhibits PPARγ activation in tumor and tumor-infiltrating macrophages." (PMID 37190200, 2023). "Results also showed that Al-BSA-Ce6 NPs could successfully induce a strong tumor immune response due to TNF-α and INF-γ production increase." (PMID 37238966, 2023).
tumor (continued). "Further immunomodulation could be caused by UNC13A, which facilitates vesicle release and positively regulates TNF-α secretion from activated macrophages, thereby decreasing cytotoxic T-cell activity and increasing tumor growth." (PMID 37444464, 2023). "Meanwhile, we analyzed the cytokines in the tumor by ELISA, and the analysis showed that the combination therapy significantly increased the immunostimulatory cytokines (TNF‐α, IFN‐γ, and IL‐12) and decreased the immunosuppressive cytokines (IL‐10 and TGF‐β) compared with the monotherapy." (PMID 37552209, 2023). "In summary, TNF-α enhances the anti-tumor capacity of MSCs via a variety of mechanisms." (PMID 36814921, 2023). "TNF-α is a pro-inflammatory cytokine that is present in the tumor microenvironment." (PMID 37041130, 2023). "However, TNF-α-stimulated MSCs mainly exhibit anti-tumor capacity, principally by: 1) enhancing the inflammatory response to eliminate tumor cells; 2) releasing tumor apoptotic factors, such as IP10 and TRAIL; and 3) blocking the tumor cell cycle." (PMID 36814921, 2023). "However, the three doses of H. junceus scorpion venom tested significantly decreased (p < 0.05) the levels of TNF-α in the serum of BALB/c mice implanted with the F3II tumor." (PMID 38137888, 2023). "Moreover, vagal stimulation reduces the levels of pro-inflammatory cytokines (e.g., interleukin-1β and tumor necrosis factor-α), and enhances anti-tumor immunity by activating cytotoxic CD8+ T cells and NK cells." (PMID 37371563, 2023). "Thus, in this context, TNF-α can recruit a subpopulation of myeloid tumor cells with significant pro-cancer effects." (PMID 36814921, 2023). "Additionally, a positive feedback loop was described, including IL6/STAT3, IL1/NF-κB, and TNF/AP-1 signaling pathways, which maintain the state of inflammation in the tumor." (PMID 36825204, 2023). "At least some of this heterogeneity may be attributable to technical differences across patients, including treatment efficacy, with pro-tumoral molecules, including TNF-alpha, significantly higher among patients with subsequent tumor recurrence." (PMID 36969248, 2023). "However, P2RX7s have been shown to promote the release of pro-inflammatory cytokines, including interleukin (IL)-1β, IL-6, and tumor necrosis factor (TNF)-α, which would limit tumor growth." (PMID 37241023, 2023). "In addition, important tumor pathways, such as Wnt, MAPK, Notch, JAK-STAT, PD-1/PD-L1, mTOR, TNF, HIF-1, and ErbB, are all related to the risk score, and pathways and functions related to disulfidptosis and ferroptosis are also related to the risk score." (PMID 37946181, 2023). "TNFα tumor cells exhibiting constitutive expression of TNFα." (PMID 37331004, 2023). "Notably, TNF blockade effectively rescued this impairment, indicating that tumor‐derived EVPs hinder liver drug metabolism via TNF‐related pathways." (PMID 38034099, 2023). "Among the commonly used immune cells, macrophages are intensively employed as the research model for the antitumor activity of oligosaccharides in vitro as activated macrophages can release tumor necrosis factor-α (TNF-α), a crucial cytotoxic mediator that can wreck tumor cells." (PMID 37432179, 2023). "TNF-α can enhance tumor invasion by affecting angiogenic factors." (PMID 37927462, 2023). "TNF-α is involved in the human body’s defense against infection and anti-tumor effects through the expression of cell-adhesion molecules, the induction of apoptosis, the production of inflammatory mediators, and the enhancement of antibody production by plasma cells." (PMID 38004064, 2023). "The M2d macrophages play an important role in tumor progression and are characterized by increased IL-10 and VEGF secretion and decreased expression of IL-12 and TNF-α, however, the specific mechanism underlying programming the M2d macrophages remains controversial." (PMID 36845095, 2023).